IFNAR2 (interferon alpha and beta receptor subunit 2)
Diseases named in the same sentence as IFNAR2 in open-access papers (continued):
Sharing a sentence is not in itself a finding about the gene and the disease.
COVID-19 (continued). "Notably, IFNAR2 variants demonstrated monocyte-specific, COVID-19-related quantitative expression trait effects, highlighting the influence of host genetic variation on immune cell behavior and disease severity." (PMID 40543387, 2025). "Also, variants rs17860118 and rs2229207 in the IFNAR2 gene have been conclusively linked with susceptibility to SARS-CoV-2 in COVID-19 patients (OR = 1.718, CI 95% = 1.039-2.841, P = 0.033, and OR = 1.89, CI 95% = 1.141-3.156, P = 0.012, respectively)." (PMID 39351231, 2024). "To address this question, in this study, we investigated whether the IFNAR2 polymorphism was associated with interferon signaling in patients with COVID-19 by analyzing the induction of ISGs expression." (PMID 39435115, 2024). "However, at least, impaired IFNAR signaling due to decreased IFNAR2 expression appears to be associated with COVID-19 severity, as supported by various studies." (PMID 39351231, 2024). "Importantly, this SNP is also associated with COVID-19 severity and hospitalisation, and this SNP also contributes to the expression of IFNAR2 gene together with rs2236757." (PMID 39435115, 2024). "Despite the strong association between IFNAR2 polymorphism (rs2236757) and COVID-19 severity, it remains unclear whether this polymorphism interferes with interferon signaling and immune response in patients with COVID-19." (PMID 39435115, 2024). "Likewise, various studies employing diverse methodologies have corroborated the significance of IFNAR2 as a crucial gene implicated in the severity of COVID-19." (PMID 37632067, 2023). "The relevance of studying genetic variants in IFNAR1 and IFNAR2 in patients with COVID-19 is that there are previous reports of polymorphisms in these genes associated with response to interferon therapy, like rs9984273 (IFNAR2) located in a binding motif for the glucocorticoid receptor." (PMID 38003785, 2023). "Notably, rs2236757 was the most replicated in the Caucasian population; this variant did originate from Mendelian randomization (MR) analysis and showed evidence that lower expression of IFNAR2 is associated with life-threatening COVID-19." (PMID 38003785, 2023). "Therefore, based on the model, the key components of COVID-19 susceptibility in childhood are alleles of genes IFNAR2 rs2236757, OAS1 rs10774671, OAS3 rs10735079, CD40 rs4813003 and CASP3 rs113420705." (PMID 37896870, 2023). "This leads to a hypothesis that COVID-19 patients harboring IFNAR2 rs9975538 variant might be more likely to develop neurological disorders, possibly though neuroinflammatory pathways." (PMID 36531218, 2022). "Likewise, other studies using different methodologies have identified IFNAR2 as an important causal gene of COVID-19 severity, although the levels of the soluble receptor have not been determined." (PMID 35967349, 2022). "In coronavirus disease 2019 (COVID-19), IFNAR2 has demonstrated relevance in the available genetic association studies." (PMID 35967349, 2022). "However, both IL10RB and IFNAR2 GReX are associated with more severe COVID-19 clinical outcomes in EUR, participants of African descent (AFR), and in the trans-ethnic meta-analyses (ordinal logistic regression)." (PMID 36064543, 2022). "Genetic association study of IFNAR2 variants with mortality in patients with severe COVID-19." (PMID 35967349, 2022). "These miRNAs target several pro-inflammatory cytokine and chemokine genes (e.g., TNF, CCL2, CXCL9, CXCL10, IL10, VEGFA) as well as cytokine and chemokine receptors and transduction factors (IL1R1, IL2RA, IFNAR2), reported as upregulated and associated with mortality in COVID-19 patients." (PMID 36032130, 2022). "Moreover, evidence in support of a causal link betweenlow expression of IFNAR2 and high expression ofTYK2 with life-threatening COVID-19 was reported." (PMID 34436508, 2021).
COVID-19 (continued). "H3K27ac HiChIP-based chromatin-interaction maps in NK cells showed that multiple cis-regulatory regions, including the IFNAR2 promoter, harbor COVID-19-risk eQTLs and directly or indirectly interact with the IL10RB promoter and potentially influence its expression." (PMID 34799557, 2021). "Given that more than 10% of the COVID-19 diagnosed individuals requiring hospitalization reported migraine and headache symptoms, reduced host expression of IFNAR2 may also modulate risk for migraine symptoms in the context of severe COVID-19 infection." (PMID 34315903, 2021). "One of the main challenges of our analysis was to determine whether IFNAR2 or IL10RB (or both) was driving the association with COVID-19 hospitalization, given that they share cis-eQTLs used as proposed instruments for our MR analysis." (PMID 33837377, 2021). "In addition, the risk of severe COVID-19 was inversely associated with IFNAR2 mRNA expression." (PMID 41596638, 2026). "Taken together, the risk allele of rs13050728 might contribute to severe COVID-19 by increasing expression of IFNAR2 in cMono, highlighting the importance of context and cell type-specific eQTL analysis to elucidate host genetical effects in pathophysiology of COVID-19." (PMID 37095364, 2023). "Based on a large-scale meta-analysis (N = 680,128), our group found that the IFNAR2-IL10RB gene cluster was significantly associated with COVID-19 susceptibility, and suggested that IFNAR2 and IL10RB might have regulatory roles in the pulmonary immune response based on scRNA-seq data." (PMID 35172892, 2022). "Hence, the rs2236757 polymorphism might decrease IFNAR2 expression, consequently predisposing patients to severe forms of COVID-19." (PMID 36672770, 2022). "Numerous studies have investigated the role of the Interferon Alpha and Beta Receptor subunit-2 (IFNAR2) gene in the context of COVID-19." (PMID 40543387, 2025). "The surface monocyte CD64, CD16, and IFNAR2 were all higher in the very early phase of COVID-19 and did correlate with each other." (PMID 40710346, 2025). "We uncovered gene-regulatory mechanisms at disease loci with therapeutic implications, such as WARS1 in hypertension, IL7R in dermatitis and IFNAR2 in COVID-19." (PMID 40038547, 2025). "A further key COVID-19 GWAS locus demonstrating context-specific activity is rs6517156, which forms a gQTL for IFNAR2 post IFN-γ (FDR 6.2 × 10−6), again emphasising the importance of the IFN-γ stimulus to elucidation of the COVID-19 disease state." (PMID 41022800, 2025). "In COVID-19 patients who also had type 2 diabetes, our results indicated that patients carrying the minor variants of LZTFL1 and RAVER1 (and probably also IFNAR2 and MUC5B) are more likely to have hospitalization-requiring COVID-19 than the general population." (PMID 39752416, 2025). "This study investigated the associations between interferon-stimulated genes (ISGs) expression, genetic variation in the interferon α/β receptor 2 (IFNAR2) gene, and COVID-19 mortality." (PMID 39435115, 2024). "The distribution of genotypes for the ACE2 rs2074192, IFNAR2 rs2236757, OAS1 rs10774671, and OAS3 rs10735079 polymorphisms conformed to HWE in both the COVID-19 and control groups (p > 0.05)." (PMID 39296547, 2024). "To offer potential therapeutic strategies and contribute to better patient care and treatment decisions, we would like to summarize the current findings on the association of IFNAR2 and TYK2 genes with COVID-19 pathology and propose future challenges." (PMID 39351231, 2024). "Literature examples of this in COVID-19 severity include a DOCK2 gene variant in East Asians and frequent loss-of-function variants in IFNAR1 and IFNAR2 genes in Polynesian and Inuit populations, respectively." (PMID 39361370, 2024). "A significant finding emerged when comparing COVID-19 patients with controls, which demonstrated lower gene expressions of IFNAR2 and TYK2 in COVID-19 cases." (PMID 38741892, 2024).
COVID-19 (continued). "The study showed that low IFNAR2 expression and high TYK2 expression levels are linked to COVID-19 severity." (PMID 39435115, 2024). "In severe COVID-19 cases, higher levels of soluble IFNAR2 (sIFNAR2) have been observed, which can bind to IFNs and prevent them from interacting with cell surface receptors, thus impairing the signaling pathway." (PMID 39351231, 2024). "Previous research has highlighted the strong connection between a genetic marker, rs13050728, and severe COVID-19 cases, influencing the expression of a key immune gene called interferon alpha receptor 2 (IFNAR2)." (PMID 38915416, 2024). "We propose that interference with IFN α and IFN β hinders type I interferon response, impacting COVID-19 severity and increasing IFNAR2 expression." (PMID 38915416, 2024). "A gene-based association test revealed a significant association in BAZ2B and in previously known COVID-19 risk loci: LZTFL1, XCR1, FYCO1, CCR9, and IFNAR2." (PMID 39361370, 2024). "Evidence highlighting the significance of IFNAR2’s role in COVID-19 severity spans various studies, ranging from genetic and transcriptional levels to soluble protein dynamics." (PMID 38741892, 2024). "Compared to IFNAR2, studies of genetic variants of IFNAR1 and COVID-19 had a small sample size; however, the results in IFNAR1 and infection by SARS-CoV-2 are relevant." (PMID 38003785, 2023). "In a subset of 79 children, a genetic analysis was carried out to evaluate the role of common COVID-19 genetic risk factors (chromosome 3 cluster; ABO-blood group system; FUT2, IFNAR2, OAS1/2/3, and DPP9 loci)." (PMID 36873632, 2023). "The study revealed that ACE2 rs2074192 (allele T), IFNAR2 rs2236757 (allele A), OAS1 rs10774671 (allele A), CD40 rs4813003 (allele C), CASP3 rs113420705 (allele C) and male sex contribute to severe COVID-19 course and MIS-C in 85.6% of cases." (PMID 37896870, 2023). "The multifactorial analysis shows that, in addition to ACE2, IFNAR2, OAS1, and CD40 genes, the CASP3 rs113420705 gene (allele C) makes the clinical outcome of COVID-19 in males worse." (PMID 37896870, 2023). "Logistic regression analysis under five genetic models adjusted for age, sex, smoking history, DM, hypertension, and CAD was used to investigate the association of IFNAR2 rs2236757 and OAS3 rs10735079 polymorphisms with COVID-19 signs and symptoms." (PMID 37745867, 2023). "IFNAR2 is important in COVID-19, as evidenced by type-I IFN gene expression decreasing following SARS-CoV-2 infection." (PMID 38003785, 2023). "Colocalization did not appear to depend on SARS-CoV-2 PCR result in BQC19 among individuals with symptoms of COVID-19, as seen with IFNAR2." (PMID 37640912, 2023). "Such indicators as male sex, ACE2 rs2074192 allele T, IFNAR2 rs2236757 allele A, OAS1 rs10774671 allele A, CD40 rs4813003 allele C and CASP3 rs113420705 allele C can predict severe COVID-19 course and MIS-C in the pediatric population in 85.6% of cases." (PMID 37896870, 2023). "Recent genome-wide analyses of COVID-19 patients have revealed that SNP rs2236757 in IFNAR2 has a significant impact on disease severity, but the functional role of these findings is yet to be explained and the contribution to signaling remains to be revealed." (PMID 36927455, 2023). "DE analysis revealed increased IFNAR2 expression in cMono of COVID-19 patients than healthy controls (P = 1.7 × 10−5), consistent with previous findings." (PMID 37095364, 2023). "IFNAR2 and IFNAR1 genes have been associated with severe COVID-19 in populations from the United Kingdom, Africa, and Latin America." (PMID 38003785, 2023). "By leveraging summary statistics from a COVID-19 GWAS and a Mendelian randomization approach, a recent drug repurposing study prioritized IFNAR2 as one of top two candidate drug targets for early management of COVID-19." (PMID 36167494, 2022).
COVID-19 (continued). "In this work, we detected the clinical significance of IFNAR2 (2 SNPs), SLC6A20 (1 SNP) with respect to COVID-19 susceptibility and ADAM17 (2 SNPs), TMPRSS2 (1 SNP), TYK2 (1 SNP), DPP9 (1 SNP) with respect to the severity of the disease." (PMID 36292769, 2022). "Our study shows that the rs1799752/ACE1, rs1990760/IFIH1, rs2236757/IFNAR2, rs12329760/TMRPSS2, and rs2304256/TYK2 polymorphisms are genetic risk factors for severe forms of COVID-19 and increased mortality." (PMID 36672770, 2022). "Collectively, our association analyses highlighted six common variants identified in previous GWAS or by the HGI—in/near LZTFL1, MHC, DPP9, IFNAR2, RPL24 and FOXP4—that are associated with COVID-19 as well as disease severity among cases." (PMID 35241825, 2022). "In COVID-19, the IFNAR2 (interferon alpha and beta receptor subunit 2) gene has been associated with the severity of the disease, but the soluble receptor (sIFNAR2) levels have not been investigated." (PMID 35967349, 2022). "Next, we assessed how the expression of IFNAR2 on these immune cell subsets differed between the unexposed healthy controls and the different COVID-19 severity groups." (PMID 36433939, 2022). "In contrast to bulk transcriptomics, we show at the single-cell level that IFNAR2 is only affected on certain blood immune cell populations in individuals recovered from severe COVID-19." (PMID 36433939, 2022). "Yet, key anti-viral responses such as IFNG primarily produced by cytotoxic T cells were spared, highlighting the selective effects of combined anti-IFNAR2/Remdesivir therapy on chronic COVID-19 pathology." (PMID 35483404, 2022). "The COVID-19 Host Genetics Initiative (HG1) report concurred with the association of variants in ABO, SLC6A20, TYK2, DPP9, IFNAR2, and additionally reported a variant in Protein Phosphatase 1 Regulatory Subunit 15A (PPP1R15A) in influencing COVID-19 severity." (PMID 36143338, 2022). "By performing a MAGMA gene-level association analysis, we observed that 25 genes including CXCR6, CCR1, IFNAR2, IL10RB, and OAS1 were significantly associated with severe COVID-19 (FDR < 0.05)." (PMID 35172892, 2022). "Using our eQTL resource in conjunction with COVID-19 GWAS, we conducted MR analyses that identified seven genes, including OAS1 and IFNAR2, as putatively causal for COVID-19 severity." (PMID 36424512, 2022). "IFNAR2 was slightly reduced in several CD38low memory B cell populations severe and critical COVID-19." (PMID 36433939, 2022). "IFNAR2 was significantly upregulated in severe COVID-19 patients (FDR = 0.0075), and both OAS1 and OAS3 were upregulated in T cells from severe COVID-19 patients compared to those with mild disease." (PMID 35659055, 2022). "In this study, out of 1238 variant previously reported to be association with susceptibility and severity of COVID-19, we confirmed 49 variants, corresponding to 18 independent loci, including 3p21.31 locus, ABO, IFNAR2, TNF, APOE, and FOXP4-AS1 gene." (PMID 36531218, 2022). "Nevertheless, the present report confirms the relevance of the IFNAR2 locus in the severity and mortality of COVID-19." (PMID 35967349, 2022). "We found that polymorphisms in TMPRSS2, ACE1, IFNAR2, and IFIH1 genes are associated with worse clinical outcomes (ICU admission) and increased mortality in patients with COVID-19, and this is influenced by sex and ethnicity." (PMID 36672770, 2022). "A GWAS study using genetic data from 2244 critically ill COVID-19 patients from UK ICUs has recently identified IFNAR2 and TYK2 as candidate genes significantly associated with severe COVID-19." (PMID 36292769, 2022). "Significant associations from two genetic regions, including FOXP4-AS1 and IFNAR2, were detected that were the same as those detected by comparison of all COVID-19 patients and the general population." (PMID 35264675, 2022).
COVID-19 (continued). "Among nine genes reported in the international meta-GWAS as genes involved in the onset of COVID-19, the association of FOXP4-AS1, ABO, and IFNAR2 genes was replicated in the Japanese population." (PMID 35264675, 2022). "One upregulated DEG (EGF) and one downregulated DEG (IFNAR2) have been uncovered in COVID-19 responses in BD." (PMID 35185890, 2022). "IFNAR2, both gene, and soluble protein, are relevant in the clinical outcome of patients hospitalized with severe COVID-19." (PMID 35967349, 2022). "We found significant Mendelian randomization results for three proteins (ACE2: P=1.6×10-6, IFNAR2: P=9.8×10-11, and IL-10RB: P=2.3×10-14) using cis-eQTL genetic instruments that also had strong evidence for colocalization with COVID-19 hospitalization." (PMID 33837377, 2021). "An association study based on ~50,000 COVID-19 patients further supported the association of genetic variants in ABO, TYK2, DPP9, IFNAR2, SLC6A20 and Protein Phosphatase 1 Regulatory Subunit 15A (PPP1R15A) with the severity of COVID-19." (PMID 34575070, 2021). "To disentangle the shared eQTL signal for IL10RB and IFNAR2, we conducted phenome-wide association scans and pathway enrichment analysis, which suggested that IFNAR2 is more likely to play a role in COVID-19 hospitalization." (PMID 33837377, 2021). "Of these, nine ISGs were differentially regulated in Asymptomatic versus mild COVID-19 cases; IFNAR2, IRF2BP1, IRF4, MAVS, and TRIM14 were upregulated; whilst IRF2BP2, IRF2BPL, and SOCS3 were downregulated." (PMID 34824360, 2021). "IFNAR2 is another protein that is highly correlated with ACE2 (ρ = 0.62, FDR = 6.1E−04) and is also implicated in severe COVID-19 by GWAS and expression data." (PMID 34616619, 2021). "Mendelian randomization and transcriptome-wide association (TWAS) assays revealed a causal link between low expression of IFNAR2, high expression of TYK2 or the monocyte/macrophage chemotactic receptor CCR2 and life-threatening COVID-19." (PMID 34571706, 2021). "IFNAR2 was both upregulated in individuals with COVID-19 compared to healthy controls in most circulating cell types and highly expressed by plasmablasts, monocytes and DCs." (PMID 33879890, 2021). "This study showed that interferon α and β receptor subunit 2 gene (IFNAR2), tyrosine kinase 2 gene (TYK2) and chemokine receptor type 2 gene (CCR2) gene were associated with severity of COVID-19." (PMID 33396837, 2020). "Additionally, the A allele in IFNAR2 rs2236757 was associated with increased IL-1β and IL-12 but decreased IFN-α concentrations in pediatric COVID-19 cases." (PMID 40066463, 2025). "Collectively, these findings suggest that IFNAR2 concentrations in COVID-19 patients may serve as predictive indicators of disease progression." (PMID 40543387, 2025). "Our research indicated that certain polymorphisms in the genes ACE2 rs2074192, IFNAR2 rs2236757, OAS1 rs10774671, OAS3 rs10735079, CD40 rs4813003, FCGR2A rs1801274 and CASP3 rs113420705 could predict cytokine responses in pediatric COVID-19 patients." (PMID 40066463, 2025). "Additionally, IFNAR2 protein concentrations were found to be elevated in patients with severe COVID-19 during the early phase of symptoms, further supporting its role in disease progression." (PMID 40543387, 2025). "However, impaired IFNAR signaling and low IFNAR2 expression appear to be related to the severity of COVID-19, as supported by various studies." (PMID 38741892, 2024). "This indicates that despite causing reduced IFNAR2 expression, the rs2236757 polymorphism did not influence ISGs expression in patients with COVID-19." (PMID 39435115, 2024). "Notably, the study detected important genetic variants, such as rs13050728, that modulate the expression of interferon alpha receptor 2 (IFNAR2), indicating possible roles for immune response pathways in both COVID-19 and cancer." (PMID 38915416, 2024). "Moreover, there are several other polymorphic sites within the IFNAR2 gene that are important in COVID-19." (PMID 39435115, 2024).